IL23R (interleukin 23 receptor)
Diseases named in the same sentence as IL23R in open-access papers (continued):
Sharing a sentence is not in itself a finding about the gene and the disease.
psoriasis (continued). "Genetic polymorphisms of the IL-23R gene have been investigated in many autoimmune diseases, and researches have showed that IL-23R gene is associated with the etiology of AS, psoriasis, rheumatoid arthritis (RA), and multiple sclerosis, inflammation bowel disease (IBD)." (PMID 27902482, 2017). "For example, IL23R was reported to be associated with psoriasis by several GWAS studies." (PMID 27089880, 2016). "The low frequencies of variant in IL23R are accordingly of low risk for psoriasis in Chinese." (PMID 24971308, 2014). "Likewise, polymorphisms in the IL-23 receptor (IL-23R) have been associated with psoriasis, and blocking IL-23 is successful in the treatment of psoriasis." (PMID 25216727, 2014). "The authors also found an association between rs11209026 in the IL23R gene and psoriasis." (PMID 24069534, 2013). "Another recent study also associated rs11209026 in IL23R gene with psoriasis." (PMID 24069534, 2013). "For example, associations of IL23R could be shown for CD and UC, psoriasis and ankylosing spondylitis." (PMID 22457781, 2012). "Moreover, genetic variations that encode subunits of cytokines (IL-12B, IL-23A) or cytokine receptors (IL-23R) have been associated with immune disorders such as psoriasis and psoriatic co-morbidities, including Crohn's disease and diabetes." (PMID 22185520, 2011). "Studies are currently ongoing to investigate whether the protective IL23R gene variant might also contribute to a different disease phenotype in psoriasis, as it has been suggested in CD patients." (PMID 21364948, 2011). "Taken together, these collective findings suggest that polymorphisms in several components of the IL23/IL23R-pathway may be important for susceptibility to psoriasis." (PMID 19175939, 2009). "However, the role of the IL23R locus in psoriasis was supported through the family-based association tests (TDT), in which all of the 255 families were informative." (PMID 19175939, 2009). "IL23R also associates with psoriasis, suggesting that the gene may be an important candidate for many chronic inflammatory diseases." (PMID 19175939, 2009). "The Polymorphism of interleukin (IL)-23R and IL-23 genes, as well as other genes involved in lipid and fatty-acid metabolism, renin-angiotensin system and endothelial function, have been described in patients with psoriasis and with cardiovascular risk factors." (PMID 40977704, 2025). "In particular, polymorphism in the IL-23R and IL-23 genes, as well as other genes involved in lipid and fatty-acid metabolism, renin–angiotensin system and endothelial function, have been described in patients with psoriasis and with cardiovascular risk factors." (PMID 36012327, 2022). "Also, it seems that polymorphism in the IL-23R gene may have a role in the development of paradoxical infliximab-induced psoriasis." (PMID 32842528, 2020). "Another IL-23R gene polymorphism that may be associated with psoriasis is rs11209026." (PMID 31648514, 2019). "Initial supportive evidence for a functional role of IL-23 in psoriasis included the clinical efficacy of an anti-p40 monoclonal antibody (blocking both IL-12 and IL-23) in psoriasis and the association of a single nucleotide polymorphism in the IL23R gene in psoriasis patients." (PMID 30555460, 2018). "Considering the results for the variant encoding p.Arg381Gln in IL23R gene, we noted that Il-23R and Th17 cytokines are down-regulated after successful therapies and there are monoclonal antibodies directed against IL-12/23p40, IL-17A and IL-17RA which are effective in psoriasis." (PMID 29091937, 2017). "Importantly, in support of our linkage results, association of IL23R with psoriasis was confirmed in the Finnish case-controls, demonstrating under-transmission of previously reported protective variants and over-transmission of the corresponding risk variants." (PMID 19175939, 2009).
psoriasis (continued). "The possibility that inclusion of RF-positive patients in the current series may have diluted the observed effect of the IL12B and IL23R variants in PsA susceptibility should be considered, particularly because some of these patients may be found to have RA with coincidental psoriasis." (PMID 19035472, 2008). "Variants in the IL23R and IL12B genes have been associated with psoriasis susceptibility; however, data from Eastern European populations remains scarce." (PMID 42073384, 2026). "Although clinically distinct, psoriasis and IBD share core pathogenic mechanisms, including immune dysregulation, Th17-mediated inflammation, and overlapping susceptibility loci such as IL23R and IL12B." (PMID 41153620, 2025). "A meta-analysis identified 11 susceptibility loci shared between psoriasis and IBD, but only four—IL23R, IL12B, REL, and TYK2—showed strong overlap for CD, suggesting weaker genetic linkage compared with UC." (PMID 41153620, 2025). "IL23R (rs80174646) is a key regulator of Th17 cell differentiation and links psoriasis pathogenesis to retinal inflammation and neovascularization." (PMID 41465162, 2025). "Several SNPs used as IVs in the psoriasis MR analyses are located in or near genes with known immunological and inflammatory functions relevant to both diseases, such as IL23R, IL13, TRIM27, HLA-A, HLA-B, and TNFAIP3." (PMID 41465162, 2025). "The observed association between psoriasis and IBD is well documented and supported by shared genetic and immunologic pathways, including polymorphisms in IL23R, NOD2, and CARD9 genes." (PMID 40746559, 2025). "GWAS have identified over 40 regions associated with psoriasis, including essential genes such as IL12B, IL23R, and IL23A, underscoring the critical role of the IL-23/Th17 axis." (PMID 39364475, 2024). "Certain SNPs in genes like IL23R, FBXL19, CTLA4, SLC12A8, TAP1, and others predispose individuals to paradoxical psoriasis." (PMID 39000125, 2024). "Genome-wide association studies (GWAS) have identified numerous shared genetic regions between IBD and psoriasis, particularly highlighting key loci such as IL23R, IL12B, REL, and tyrosine kinase 2 (TYK2)." (PMID 39463646, 2024). "Variants in the IL23R gene link the pathophysiology of IBD and psoriasis, where IL-23 plays a critical role in driving immune-inflammatory pathways." (PMID 39463646, 2024). "Furthermore, the role of specific SNPs like IL-12B and IL-23R in psoriasis predisposition, and their influence on cytokine synthesis and T-cell differentiation, can provide a genetic framework that, when altered, may shift the therapeutic response spectrum of UST." (PMID 38256367, 2024). "Among the genes mapped to gene ontology biological processes and Reactome pathways, IL23R is linked to axial spondylarthritis, inflammatory bowel disease, and psoriasis, while IL36RN is associated with psoriasis." (PMID 39234544, 2024). "In another mouse model where psoriasis was induced via TLR7, CLOCK and Per2 were found to regulate the severity of psoriasis via the direct modulation of the expression of IL23R." (PMID 36982706, 2023). "Previous research has found that in people with parents suffering from psoriasis are easier to suffer from this disease, several psoriasis susceptibility genes have been identified, including HLA-Cw6, IL12B, IL23R, and LCE3B/3C." (PMID 37497220, 2023). "To date, >70 psoriasis susceptibility loci have been identified, including HLA-Cw6, IL12B, IL23R, and LCE3B/3C." (PMID 35707771, 2022). "For example, different variants in IL23R, that interfere with IL23 signaling, have protective effects not only in BD but also for ankylosing spondylitis (AS), psoriasis, and inflammatory bowel disease (IBD)." (PMID 36246630, 2022). "A previous study from our laboratory found five SNPs (rs11209026 in IL23R, rs10782001 in FBXL19, rs3087243 in CTLA4, rs651630 in SLC12A8, and rs1800453 in TAP1) associated with anti-TNF-induced paradoxical psoriasis reactions." (PMID 36143237, 2022).
psoriasis (continued). "These cytokine-signaling pathways were associated with several psoriasis susceptibility loci such as IL23A, IL23R, and NFKBIZ." (PMID 34680995, 2021). "IL-10, IL-17A, IL-17RA (interleukin 17A receptor), IL-23A (interleukin 23 subunit α) and IL-23R (interleukin 23 receptor) in the development of psoriasis." (PMID 34945130, 2021). "The present study examines the expression of the genes IL-10, IL-17A, IL-17RA, IL-23A and IL-23R in the skin and peripheral blood of patients with psoriasis and of healthy people, to identify potential factors regulating the development of psoriatic lesions." (PMID 34945130, 2021). "Intriguingly, similar findings concerning the association of psoriasis with the IL12B and IL23R gene polymorphisms were documented in previous studies." (PMID 34680995, 2021). "The IL23R SNPs identified in Crohn’s disease, ulcerative colitis, psoriasis, ankylosing spondylitis, and Behçet’s disease were located in different LD blocks from the LD blocks of the sarcoidosis-associated SNP (rs117633859) identified in this study." (PMID 32826979, 2020). "Thereof, three differentially expressed lncRNAs in proximity to known psoriasis susceptibility loci at CARD14, LCE3B/LCE3C, and IL-23R, and are thought to modulate their function." (PMID 30909615, 2019). "The CA and CC genotypes of the IL-23R gene at the rs1343152 locus were reported to be higher in psoriasis patients than in controls; however, the distribution of these genotypes was not significantly different between the patient and control groups." (PMID 31648514, 2019). "ERAP1, IL23R, and different MHC class I associations have also been reported for AS, psoriasis, and uveitis." (PMID 31849945, 2019). "The genome-wide association study (GWAS) on psoriasis risk genetic loci also indicated that IL12B and IL23R are specifically susceptible genes associated with psoriasis." (PMID 31454926, 2019). "Second, IL23R+ γδT17 cells developed from peripheral IL23R− γδ T cells during imiquimod (IMQ)-induced psoriasis." (PMID 29731754, 2018). "These include interleukin 23 receptor (IL-23R) and tumor necrosis factor alpha-induced protein 3 (TNFAIP3), which have been implicated in the development of PsA more so than in psoriasis." (PMID 29364831, 2018). "Few proposed: IL23R (an allele that is protective concerning classical psoriasis), and FBXL19, CTLA4, SCL12A8, TAPl which have an unclear role in paradoxical psoriasis and the outcome of the allele is undetermined." (PMID 30555460, 2018). "Many genes (e.g., IL-12B, IL-23A, IL-23R, TRAF3IP2, and TYK2) are significantly associated with psoriasis." (PMID 29292715, 2017). "Genetic studies that link single nucleotide polymorphisms in/near IL-23R, IL23A, IL12B, TYK2 and STAT3 with psoriasis susceptibility have highlighted IL-23 as a critical cytokine in disease pathogenesis." (PMID 26573299, 2016). "In practice, this two-model approach guiding fine mapping was successfully employed to identify alleles segregating at the TRAF1-C5 region conferring susceptibility to rheumatoid arthritis and to fine map the IL23R region in psoriasis." (PMID 28018425, 2016). "This decay pattern was first used empirically in 2007–2008 to fine map the TRAF1 region in rheumatoid arthritis and the IL23R region in psoriasis and has, in an analogous form, subsequently been used in other applications." (PMID 28018425, 2016). "Initial causative research has identified strong association between psoriasis and the interleukin genes (IL4, IL10, IL12B, IL13, and IL23R) in the northern European from US and UK." (PMID 24971308, 2014). "Other genes, such as IL23R, PSORS1C1, HCP5, were found to be associated with psoriasis and rheumatoid arthritis." (PMID 25369137, 2014). "Psoriasis has been associated with genes involved in the immune response, namely, TNFα, IL12B, and IL23R." (PMID 24069534, 2013).
psoriasis (continued). "A subsequent GWAS with 1810 cases and 2522 controls found an association between SNPs in IL23R (rs7530511 and rs11209026) and IL12B (rs6887695 and rs3212227) and predisposition to psoriasis in Caucasian patients." (PMID 24069534, 2013). "Interleukin 23 receptor (IL23R), IL12B, and the human leukocyte antigen Cw6 (HLA-Cw6) of the major histocompatibility complex have been strongly associated with psoriasis." (PMID 24069534, 2013). "Analysis of three distinct AS populations in Canada has demonstrated a disease association with the IL-23 receptor (IL-23R) locus and implicates the same polymorphism associated with IBD and psoriasis." (PMID 24286190, 2013). "Genetic variations in ERAP1, IL23R, and LCE3B/LCE3C have recently been associated with pediatric-onset psoriasis (onset < age 18) in a small study." (PMID 24175098, 2013). "Polymorphisms in IL23R and IL12B have been associated with susceptibility to psoriasis in both Caucasian and Asian patients." (PMID 24069534, 2013). "Similar to IL23R, IL12B is also a shared susceptibility gene with other IBD-associated diseases such as psoriasis and ankylosing spondylitis, providing an explanation of the increased incidence of these extraintestinal manifestations in IBD patients." (PMID 22479607, 2012). "There was a statistically significant difference between PsA and psoriasis alone at three loci (HLA-C, IL-12B and IL-23R)." (PMID 20606885, 2010). "One of the 1st AS risk loci identified, IL23R, is also associated with both forms of IBD (ulcerative colitis and Crohn's disease) as well as psoriasis." (PMID 21152001, 2010). "The IL23R region demonstrated linkage to psoriasis in the Finnish pedigrees, suggesting that the locus is involved in this inflammatory skin disorder." (PMID 19175939, 2009). "Our study set out to test the reported association of IL23R with IBD and psoriasis, using Swedish and Finnish patient materials." (PMID 19175939, 2009). "Recently, association of single-nucleotide polymorphisms (SNPs) within the interleukin-23 receptor gene (IL23R) and a gene encoding a subunit of its ligand, IL12B, have been reported to be associated with psoriasis." (PMID 19035472, 2008). "We genotyped one IL23R SNP (Arg381Gln; rs11209026), which has previously been associated with IBD and psoriasis." (PMID 18045485, 2007). "In this study, we tested three genes, namely, IL23R, IRF5 and CD40, which have been associated with other immune-mediated diseases, including Crohn's disease (CD), psoriasis, SLE and GD, for an association with type 1 diabetes." (PMID 18045485, 2007). "IL23R is a proinflammatory protumor cytokine associated with autoimmune conditions and chronic inflammatory diseases (CID), such as inflammatory bowel disease (IBD), Crohn’s disease, axial spondyloarthritis and psoriasis (Pso)." (PMID 40149697, 2025). "Additionally, the rs11209026 variant in IL23R is significantly associated with the risk of IBD, AS, and psoriasis." (PMID 39595128, 2024). "In particular, a loss-of-function mutation (R381Q) in IL-23R, which results in decreased downstream IL-17 production and reduced STAT3 activation, is protective in psoriasis and IBD17,19,21, providing the basis for IL-23R antagonism as a therapeutic approach in these diseases." (PMID 39080319, 2024). "Certain genes, like HLA-C, IL23R, IL12B, and LCE3B/3C, increase susceptibility to psoriasis." (PMID 38022642, 2023). "Recently, it was found that neutrophils also express IL‐23R,24 and the release of IL‐23 by neutrophils can bind to its surface receptor IL‐23R, which lead to self‐activation of neutrophils and further exacerbate inflammation in psoriasis." (PMID 37522489, 2023). "Specifically, IL23R encodes the interleukin 23 receptor, and risankizumab, targeting interleukin 23, was repurposed as the treatment for Crohn’s disease (a subtype of IBD) from the original usage for psoriasis." (PMID 38102678, 2023).
psoriasis (continued). "In our IL-23R top ranked list, we observed that Ustekinumab’s approved indications were among the top predicted indications on this drug target, including Crohn’s disease (10th) and Psoriasis (27th), indicating their high potential for IL-23R." (PMID 35710324, 2022). "IL‐23R− related disorders include inflammatory bowel disease and psoriasis." (PMID 36444617, 2022). "It is therefore interesting that AS does not show the same genetic association with IL23 as psoriasis, perhaps suggesting that Il-23 itself is important in psoriasis while IL23R and downstream signalling pathways are rather more relevant to the pathogenesis of AS." (PMID 33746951, 2021). "There is evidence to suggest that mutations in the interleukin-23 receptor (IL23R) gene could confer increased susceptibility to AI conditions, such as RA, psoriasis and TED, which may explain the association of RA and psoriasis in our cohort." (PMID 33746907, 2021). "The main SNP primarily associated with AS, psoriasis and IBD (rs11209026) causes a loss-of function mutation in the cytoplasmic tail of IL23R that reduces IL-17 and IL22 production by Th17 effector cells and modulates responses to pattern recognition receptors." (PMID 33746951, 2021). "Dendritic cells (DCs) secrete IL-23 to bind IL-23 receptor (IL-23R) presented on Th1, Th17, and Th22 cells, which in turn act on keratinocytes, ultimately leading to excessive proliferation of the cutaneous keratinocyte to form psoriasis." (PMID 34483908, 2021). "In the same study, a specific association was also found with a variant of IL23R (rs12044149), independent of a psoriasis-associated variant in the same gene (rs9988642)." (PMID 26255310, 2016). "The many genetic studies performed in recent years showed that genes such as interleukin 23 receptor (IL23R) and IL12B and tumor necrosis factor alpha (TNFα) are closely associated with psoriasis and related diseases such as rheumatoid arthritis, psoriatic arthritis, and Crohn's disease." (PMID 26613086, 2015). "The nonsynonymous SNP in IL23R, rs11209026, widely thought to be the primary psoriasis-associated SNP in IL23R in Europeans, was found not to be polymorphic in Chinese, which is in agreement with the findings of others." (PMID 24971308, 2014). "The SNPs rs11209026 in IL23R gene and rs3212227 in IL12B gene have also been studied in Japanese patients (143 cases and 100 controls), and the A allele (rs3212227) was more frequent in patients with psoriasis than in healthy subjects." (PMID 24069534, 2013). "It is also feasible that the IL23R SNP could be used as a novel biomarker to predict therapeutic response and studies are currently ongoing to test this hypothesis in psoriasis." (PMID 21364948, 2011). "Thus far, only the gene IL23R (associated with AS) has also been found to be associated with inflammatory bowel disease (IBD) and psoriasis, although the three conditions commonly occur in the same patients, and are co-familial." (PMID 21152001, 2010). "Indeed, a recent study of UK patients with psoriasis demonstrated ORs of 1.67, 1.98, 1.38, and 1.72 for the rs11209026 and rs7530511 IL23R SNPs and the rs3212227 and rs6887695 IL12B SNPs, respectively." (PMID 19035472, 2008). "Variation within IL23R and IL12B is associated with susceptibility to both psoriasis and PsA." (PMID 19035472, 2008). "Finally, we did not obtain any evidence of an association between type 1 diabetes and IL23R, IRF5 or CD40, all of which have previously been associated with other immune-mediated diseases including, most recently, IL23R in Crohn's disease and in psoriasis." (PMID 18045485, 2007). "In addition to this, polymorphism studies have shown relationships between the IL-12B and IL-23R genes and various autoimmune diseases such as multiple sclerosis, psoriasis, rheumatoid arthritis (RA), inflammatory bowel disease, ankylosing spondylitis, sarcoidosis, arthritis and Crohn’s disease." (PMID 41596568, 2026).